SORD (sorbitol dehydrogenase)
Diseases named in the same sentence as SORD in open-access papers (continued):
Sharing a sentence is not in itself a finding about the gene and the disease.
Motor axonal neuropathy (1 paper, 2021). Progressive impairment of function of motor axons with muscle weakness, atrophy, and cramps. "All affected individuals with biallelic pathogenic mutations in SORD in this study presented with pure motor axonal neuropathy with childhood and adolescent onset, and the mean age of onset was 14 years." (PMID 34819907, 2021). "Electrophysiological studies revealed pure motor axonal neuropathy in all individuals with biallelic mutations in SORD." (PMID 34819907, 2021).
ovarian carcinoma (1 paper, 2020). A malignant neoplasm originating from the surface ovarian epithelium. "The high expression of SORD, whose related protein was detected only in EIC in our data set, in non-SOC was unexpected as the protein atlas reports low expression of SORD in ovarian cancer." (PMID 33384952, 2020).
serous ovarian carcinoma (1 paper, 2020). "SORD showed significantly lower expression levels in the normal control tissues, and to a smaller extent, in serous ovarian carcinoma compared to the other subtypes." (PMID 33384952, 2020).
Sorbitol dehydrogenase deficiency (1 paper, 2022). "Sorbitol dehydrogenase deficiency with peripheral neuropathy is associated with mutations in the SORD gene." (PMID 35436891, 2022).
type 2 diabetic (1 paper, 2008). "The data presented here show that inhibition of aldose reductase or sorbitol dehydrogenase attenuates increases in cytosolic NADH/NAD ratio in type 2 diabetic rat hearts and is associated with changes in ATP levels and protection of hearts from IR injury." (PMID 18957123, 2008). "The data presented here demonstrates that flux via aldose reductase and sorbitol dehydrogenase is increased in type 2 diabetic rat hearts and that these increases play key roles in determining the extent of ischemic damage." (PMID 18957123, 2008).
tumor (12 papers, 2011 to 2025). "In the tumor cell, the IHC expression of SORD was significantly lower in the group with BM than that in the group without BM (p = 0.017)." (PMID 34503278, 2021). "Several of the understudied genes are directly involved in critical metabolic pathways of tumor etiology, including glucose metabolism (SORD), lipid biosynthesis (FAR1), cAMP signaling pathway (PDE7A, ADCY6), and glutamate anaplerosis (ABAT, GLUD1)." (PMID 31231467, 2019). "Expression intensities of SPARC, COL1A1, COL5A1, COMP, IBSP, and THBS4 were interpreted in tumor stroma, as they were associated with ECM-related pathways, and the expression intensity of SORD was interpreted in tumor cells, as it was associated with the EMT pathway." (PMID 34503278, 2021). "A recent proteomics study found that the levels of SORD expression in tumor tissue were significantly associated with prognosis in patients with HCC, implying that serum SORD levels may be used as a prognostic marker in these patients." (PMID 34885252, 2021). "In particular, this included genes involved in secretory pathways, lipid and sugar metabolism (such as, UGDH, SORD, GLUD1, ELOVL5, ASCL3, UAP1), but also genes implicated in tumor progression and metastasis with functions in cell survival, proliferation and adhesion (EHF, ELL2, TPD52, MAFB, SGK)." (PMID 21829708, 2011). "Conversely, increased sorbitol dehydrogenase (SORD) levels in HCC appear to bolster necroptotic signaling, encourage M1 macrophage polarization within the tumor milieu, and possibly restrain tumor growth." (PMID 39117626, 2024).
cancer (6 papers, 2019 to 2025). A tumor composed of atypical neoplastic, often pleomorphic cells that invade other tissues. "Polyol pathway promotes the cancer cell progression and aggressiveness through sugar alcohols produced by two enzymes: SORD and aldo-keto reductase." (PMID 36233276, 2022). "The polyol pathway, which produces sugar alcohols by aldo-keto reductase and SORD contributes to cancer development and aggressiveness." (PMID 34885252, 2021). "It is noteworthy to mention that the cancer patient was graded to be metastatic whereas two of the candidate genes (SORD and SVEP1) were able to induce EMT." (PMID 31272500, 2019). "Moreover, increased expression of aldo-reductase and SORD was observed in various cancers such as liver, breast, and colorectal cancers." (PMID 34885252, 2021). "SORD is a poorly studied gene in cancer that its expression reduction might prevent cell proliferation and EMT in CRC." (PMID 34249670, 2021). "SORD is a poorly studied enzyme in cancer, found to be upregulated in CRC." (PMID 34249670, 2021). "Additionally, activation of glycolytic pathways such as the polyol pathway in cancer cells, of which SORD is a key enzyme, may contribute to further accumulation of sorbitol, promoting the poor differentiation of HCC." (PMID 34885252, 2021). "To conclude, SORD might be a remarkable biomarker for HCC in the late stage, which shows more cancer aggressiveness that might be related to drug resistance in HCC." (PMID 36233276, 2022).
peripheral neuropathy (3 papers, 2022 to 2024). A disorder affecting the peripheral nervous system. "Recently, the SORD gene has been considered one of the most frequent causative genes for autosomal recessive axonal CMT or dHMN, which share a phenotype of motor-predominant peripheral neuropathy." (PMID 37519884, 2023).
infection (2 papers, 2018 to 2021). The state of being infected such as from the introduction of a foreign agent such as serum, vaccine, antigenic substance or organism. "In conclusion, we found low uptake of 3H-sorbitol and FDS by A. fumigatus cultures and infection models compared with E. coli, likely due to the need for induction of sorbitol dehydrogenase by sorbitol." (PMID 35049965, 2021).
neurological diseases (1 paper, 2022). "We used whole-exome sequencing technology to screen the full-length SORD gene in 601 Chinese sporadic ALS patients and 174 controls without a history of neurological diseases." (PMID 36431311, 2022).
SORD also shares sentences with these, for which no sentence is quoted: Hepatic steatosis (2 papers); and sensory neuropathy (1); atherosclerosis (1); breast carcinoma (1); bronchiectasis (1); cataract (1); cholestasis (1); cognitive decline (1); colorectal cancer (1); Ewing sarcoma (1); galactosemia (1); hepatocellular carcinoma (1); hereditary spastic paraplegia (1); HTLV infection (1); hyperlipidemia (1); Intellectual disability (1); juvenile amyotrophic lateral sclerosis (1); Kennedy disease (1); liver cancer (1); liver neoplasm (1); multiple sclerosis (1); Nephropathy (1); Obesity (1); osteoporosis (1); prostate adenocarcinoma (1); retinopathy (1); Sepsis (1); Stroke (1); subarachnoid haemorrhage (1); thyroid cancer (1).